INPP5K (inositol polyphosphate-5-phosphatase K)
Description:
Inositol 5-phosphatase which acts on inositol 1,4,5-trisphosphate, inositol 1,3,4,5-tetrakisphosphate, phosphatidylinositol 4,5-bisphosphate and phosphatidylinositol 3,4,5-trisphosphate. Has 6-fold higher affinity for phosphatidylinositol 4,5-bisphosphate than for inositol 1,4,5-trisphosphate. Negatively regulates assembly of the actin cytoskeleton. Controls insulin-dependent glucose uptake among inositol 3,4,5-trisphosphate phosphatases; therefore, is the specific regulator for insulin signaling in skeletal muscle (By similarity).
Synonyms: PPS; SKIP; MDCCAID
Tractability: Antibody: its Gene Ontology location is reachable by antibodies, with high confidence. PROTAC: ubiquitination databases record sites on it; its protein half-life has been measured.
Gene: Protein-coding gene on chromosome 17 (1,494,575 to 1,516,742, reverse strand). Ensembl gene ENSG00000132376.
Subcellular location: Endoplasmic reticulum; Cytoplasm
Pathways (Reactome):
Metabolism: Synthesis of PIPs at the plasma membrane
Gene Ontology:
Molecular function: inositol bisphosphate phosphatase activity; inositol trisphosphate phosphatase activity; inositol-1,3,4,5-tetrakisphosphate 5-phosphatase activity; inositol-1,4,5-trisphosphate 5-phosphatase activity; phosphatidylinositol phosphate 5-phosphatase activity; phosphatidylinositol trisphosphate phosphatase activity; phosphatidylinositol-3,4,5-trisphosphate 5-phosphatase activity; phosphatidylinositol-4,5-bisphosphate 5-phosphatase activity; protein binding; lipid phosphatase activity; vasopressin receptor activity; inositol-polyphosphate 5-phosphatase activity; phosphatase activity
Biological process: cellular response to epidermal growth factor stimulus; cellular response to insulin stimulus; cellular response to tumor necrosis factor; host-mediated suppression of viral transcription; negative regulation of calcium ion transport; negative regulation of D-glucose transmembrane transport; negative regulation of glycogen biosynthetic process; negative regulation of insulin receptor signaling pathway; negative regulation of phosphatidylinositol 3-kinase/protein kinase B signal transduction; negative regulation of protein targeting to membrane; negative regulation of single stranded viral RNA replication via double stranded DNA intermediate; negative regulation of stress fiber assembly; phosphatidylinositol dephosphorylation; ruffle assembly; actin cytoskeleton organization; cellular response to cAMP; cellular response to hormone stimulus; G protein-coupled receptor signaling pathway; glucose homeostasis; negative regulation of dephosphorylation; negative regulation of DNA-templated transcription; phosphatidylinositol biosynthetic process; positive regulation of DNA-templated transcription; positive regulation of renal water transport; positive regulation of urine volume; and 7 more
Cellular component: cytoplasm; cytosol; endoplasmic reticulum; membrane; neuron projection; nucleus; perinuclear region of cytoplasm; plasma membrane; ruffle; ruffle membrane; trans-Golgi network
Genetic constraint (gnomAD): Loss-of-function variants: 36 observed, 42.69 expected, observed/expected ratio (o/e) 0.84, 90% interval 0.64 to 1.11. The upper end of that interval is the gene's LOEUF score, 1.11, which puts it in group 4 of 6, group 1 being the genes least tolerant of losing a copy. Missense variants: 532 observed, 559.71 expected, observed/expected ratio (o/e) 0.95, 90% interval 0.88 to 1.02. Synonymous variants: 238 observed, 223.63 expected, observed/expected ratio (o/e) 1.06, 90% interval 0.96 to 1.18.
Homologues: Orthologues: chimpanzee INPP5K (99% identical), macaque INPP5K (96% identical), dog INPP5K (78% identical), mouse Inpp5k (76% identical), rat Inpp5k (75% identical), pig INPP5K (73% identical), rabbit INPP5K (73% identical), guinea pig INPP5K (70% identical), tropical clawed frog inpp5k (51% identical), zebrafish inpp5ka (47% identical), zebrafish inpp5kb (42% identical), Drosophila melanogaster CG9784 (30% identical), and 5 more. Paralogues in human: INPP5J (45% identical), INPP5B (28% identical), OCRL (27% identical), SYNJ1 (25% identical), SYNJ2 (25% identical), INPPL1 (22% identical), INPP5D (20% identical), INPP5E (19% identical), INPP5F (18% identical), FIG4 (15% identical), SACM1L (11% identical), SH2D1B (5% identical), and 1 more.